INS (insulin)
Diseases named in the same sentence as INS in open-access papers (continued):
Sharing a sentence is not in itself a finding about the gene and the disease.
Insulin resistance (continued). "We found that the PCoA2 was significantly correlated with obesogenic phenotypes (fat gain, fat mass, and relative fat mass), fatty liver score, and insulin resistance parameters (fasting insulin and HOMA-IR)." (PMID 35670534, 2022). "In the early stages of insulin resistance, pancreatic β-cells compensate for hyperglycemia by oversecreting insulin." (PMID 35834023, 2022). "Accumulating data suggests that AD is closely related to insulin resistance and the dysfunction of both insulin signaling and glucose metabolism in the brain." (PMID 35406040, 2022). "The progression of T2D reflects a slow decline in islet β‐cell function and an inability to secrete sufficient insulin in response to peripheral insulin resistance." (PMID 36245259, 2022). "This sets up a vicious cycle where selective insulin resistance results in more insulin release and higher insulin levels in turn drive more lipid deposition with a further decline in the function of adipose cells." (PMID 34863942, 2022). "IR (homeostasis model assessment of insulin resistance (HOMA-IR) was estimated from fasting serum insulin and glucose)." (PMID 36010082, 2022). "By regulating lysine biosynthesis and degradation, insulin secretion level can be improved, insulin resistance index can be reduced, islet β cell function index can be increased, and insulin resistance can be alleviated." (PMID 35571892, 2022). "First, exercise helps to reduce insulin resistance and to improve insulin sensitivity because exercise increases glucose uptake without insulin dependence." (PMID 36429358, 2022). "In vitro and rodent models suggest that arsenic impairs glucose homeostasis by acting to both increase insulin resistance and decrease insulin secretion." (PMID 35031057, 2022). "Insulin resistance along with elevated circulating insulin levels induces increased androgen production from the theca cells and abnormal changes in the lipid metabolism." (PMID 35642189, 2022). "Cardiometabolic risk factors commonly found in children with overweight or obesity are hypertension, dyslipidemia, increased fasting insulin, and insulin resistance." (PMID 35276899, 2022). "Insulin resistance is classically defined as the failure of insulin to promote its metabolic activity in organs and tissues, such as the liver, the skeletal muscle, and the adipose tissue." (PMID 36159483, 2022). "Epinephrin tends to impair insulin secretion, while norepinephrine tends to promote insulin resistance." (PMID 35669692, 2022). "The results showed that consumption of lettuce biofortified with molybdenum for 12 days did not affect beta cell function but significantly reduced fasting glucose, insulin, insulin resistance and increased insulin sensitivity in healthy people." (PMID 35405964, 2022). "In contrast, indirect evidence suggests that through AT1R mediated-activation, Ang II decreases insulin sensitivity and promotes insulin resistance in adipose tissue." (PMID 35682723, 2022). "CTPG ameliorated HFD-induced hyperinsulinemia, hyperglycemia, inflammation and insulin resistance by activating IRS1/Akt/GLUT4 insulin signaling pathway in white adipose tissue." (PMID 36229811, 2022). "The FKO mice not only showed increased circulating glucose levels, impaired glucose tolerance, and insulin resistance, but also increased circulating insulin levels under HFD challenge, suggesting a worsened condition in response to the nutritional stress." (PMID 35459739, 2022). "School feeding was positively associated with an insulin resistance marker, decreasing by 0.135 units of HOMA-IR (95% CI; −0.19, −0.08), 0.469 μU/L of insulin levels (95% CI; −0.66, −0.28), and 0.634 mg/dL of blood glucose (95% CI; −0.87, −0.39)." (PMID 36078265, 2022). "The homeostasis model assessment of β-cell function (HOMA2-β), insulinogenic index (IGI), and insulin secretion/insulin resistance index (ISSI-2) were worse in the pre-DM and NOD groups compared with NGT group (all P < 0.05)." (PMID 36387859, 2022).
Insulin resistance (continued). "In HFD-induced obese mice, overexpressing VEGF-D increases lymphatic density in adipose tissue, which lowers local immune cell buildup and improves systemic metabolic response by reducing insulin resistance and enhancing insulin sensitivity." (PMID 35252405, 2022). "Nutrition-induced insulin resistance significantly affects the insulin signaling pathways within the brain." (PMID 36358526, 2022). "It is not inconceivable that the high-fat diet in the Iraqi population is a promotor for insulin secretion and subsequent earlier development of insulin resistance and T2D." (PMID 35927727, 2022). "We also found a positive correlation between Body Mass Index (BMI), Cys, GSH, and Hcy levels, between insulin and Cys levels, and between BMI and the homeostasis model assessment-estimated insulin resistance (HOMA-IR) with 8-isoprostane levels." (PMID 36079892, 2022). "PCOS is a multisystem disorder with tissue-selective insulin resistance, where reproductive actions of insulin persist in ovaries, contrary to insulin-resistant tissues in the presence of abundant insulin levels." (PMID 35739998, 2022). "It is manifested as chronic hyperglycemia caused by defective insulin secretion, progressive development of insulin resistance, and an inadequate compensatory insulin secretory response." (PMID 35463946, 2022). "Reduced PI3K phosphorylation in AD leads to impairments in the insulin signaling pathway and consequent insulin resistance, which correlates with synaptic dysfunctions and impaired memory in AD." (PMID 36012331, 2022). "These insulin sensitivity subgroups were defined by taking the highest and lowest tertile of individuals based on an independent measure of insulin resistance." (PMID 36281448, 2022). "First, we were unable to compare the predictive power of different methods for assessing insulin resistance in our observational study, since fasting insulin levels were unavailable for most subjects." (PMID 36329456, 2022). "In terms of ITT, the mice in the HH group developed insulin resistance indicated by slowed glucose clearance after insulin administration and larger ITT AUC compared to LL." (PMID 35736495, 2022). "As a common animal model of type 2 diabetes, ZDF rats exhibit the same insulin resistance and reduced insulin production as human patients." (PMID 35581617, 2022). "The significance of oleic acid in decreasing insulin resistance and enhancing insulin transport in diabetics has been studied extensively." (PMID 36358944, 2022). "T2D is characterized by a decrease in β‐cell mass, impaired insulin secretion, and insulin resistance resulting from impaired β‐cell function." (PMID 34984701, 2022). "In acromegaly, insulin resistance due to the insulin-antagonistic effects of excess GH is compensated for by an increase in β-cell function and insulin secretion." (PMID 35355553, 2022). "Reduced insulin resistance leads to increased insulin sensitivity, which stimulates the production of endothelial NO, thus preventing EDCF production." (PMID 35622745, 2022). "Among them, 47 DMPs were significantly correlated with the expression of 36 corresponding genes, which were enriched in ‘insulin resistance’, ‘insulin signaling pathway’, and the ‘apelin signaling pathway’." (PMID 35685467, 2022). "STK24 as a member of the mammalian Sre20 kinase family can improve the insulin resistance by inhibiting the insulin signaling pathway, as we all know that insulin resistance is one of the key factors of myocardial fibrosis in DCM." (PMID 35096111, 2022). "We found that PSS alleviated hepatic insulin resistance, repaired islet beta cells, and enabled insulin to play its biological role normally." (PMID 36558381, 2022). "ER stress is reported to perturb hepatic insulin response metabolism while promoting insulin resistance." (PMID 35513574, 2022).
Insulin resistance (continued). "Subjects with insulin resistance display impaired phenotypic flexibility as a consequence of a reduced capacity for insulin-stimulated glucose uptake into muscle and adipose tissue and insufficient suppression of hepatic gluconeogenesis." (PMID 35774538, 2022). "OB-participants showed significantly higher levels of leptin, insulin, Homeostatic-Model Assessment of Insulin Resistance (HOMA-IR), and TG." (PMID 36355134, 2022). "Insulin resistance (IR) is defined as the reduction of the tissue’s response to insulin action, and it is the opposite of insulin sensitivity (IS)." (PMID 35065638, 2022). "Despite insulin resistance, chronic hyperglycemia can nevertheless result in a temporary insulin deficit (also known as glucose toxicity) with a low initial plasma insulin concentration." (PMID 36204023, 2022). "SAMP8 mice at 10 months of age show increased insulin resistance with elevated plasma insulin levels together with a reduced content in the endocrine pancreas due to the exhaustion of β-cells by the maintained increased synthesis." (PMID 35887196, 2022). "Metformin is shown to decrease gluconeogenesis, improve insulin resistance, decrease circulating insulin levels, and exert an inhibitory effect on the proliferation, and invasiveness of EC cells in preclinical studies." (PMID 36358604, 2022). "Though HOMA-IR is considered to be a measure of hepatic insulin resistance it has been found to correlate well with insulin sensitivity measures from the hyperinsulinemic-euglycemic clamp, for example." (PMID 36148302, 2022). "These cytokines were related to the destruction of intracellular insulin signal and production of insulin resistance." (PMID 36131931, 2022). "Our study is aimed at investigating the effect of C. lacerata on improving glycemic markers, insulin resistance, and insulin sensitivity of T2DM patients through a 12-week randomized, double-blind, placebo-controlled clinical trial." (PMID 35242882, 2022). "These include hepatic Insr down-regulation, reduced insulin signaling and development of insulin resistance, impaired glucose tolerance, BW gain, dyslipidemia, liver fat accumulation and increased risk of NAFLD/NASH." (PMID 36580474, 2022). "Compensatory insulin secretion is increased during obesity-induced insulin resistance; this is beneficial for blood glucose absorption to reduce blood glucose levels." (PMID 36295827, 2022). "This oxidant stress in conjunction with TNFα activity promotes JNK and IKKβ activation in adipocytes, which in turn induces adipocyte insulin resistance via IRS-1 phosphorylation—a pathway homologous to that seen in insulin resistant skeletal muscle." (PMID 36135209, 2022). "Among these dysfunctional brain insulin signaling, termed “brain insulin resistance,” is an important etiological factor in AD." (PMID 36589543, 2022). "Several studies have shown that a high-fat diet (HFD) induces glucose intolerance accompanied by insulin resistance, while still maintaining normoglycemia with an increased β cell mass and total insulin levels." (PMID 35563490, 2022). "TNF-α and IL-6, as proinflammatory factors, from obese adipose tissue contribute to insulin resistance by impairing insulin receptor activation, upregulating insulin and insulin-like growth factor-1 (IGF-1) levels." (PMID 35964108, 2022). "Serum glucose, insulin, insulin resistance (HOMA-IR), and cardiac enzymes (CK-MB and lactate dehydrogenase (LDH) are measured." (PMID 35888760, 2022). "Batf3-/- mice had significantly higher blood glucose concentration after i.p. injection of insulin compared to WT mice at 16 weeks, indicating insulin resistance in these mice." (PMID 35812447, 2022). "A study from Italy showed that LAP was a more reliable discriminator of insulin resistance in clinical settings (AUC: 0.728 [0.692–0.762]), and had a stronger correlation with insulin compared with TyG, TG/HDL-C and VAI, which is in accord with our findings." (PMID 35175162, 2022).
Insulin resistance (continued). "Meanwhile, excessive oxidative stress, induced by vascular MRs, activates redox-sensitive serine kinases and induces the serine phosphorylation of IRS-1, resulting in impaired vascular insulin metabolic signaling and insulin resistance." (PMID 36012219, 2022). "Both human and animal experiments have shown a positive correlation between GRP78 levels and insulin resistance and effective improvement in insulin sensitivity and glycemic control via GRP78 down-regulation." (PMID 36498048, 2022). "In particular, the pecan-enriched diet significantly reduced fasting insulin and insulin resistance (evaluated as homeostatic model assessment, HOMA), while improving b-cell function (assessed as HOMA-β)." (PMID 36118764, 2022). "Lipid accumulation in the liver and muscle also inhibits insulin action in these cells, leading to insulin resistance." (PMID 36497154, 2022). "Disordered BCAA metabolites can block insulin signaling and disturb lipid metabolism, resulting in insulin resistance and excessive lipid accumulation, respectively." (PMID 36619558, 2022). "As the largest organ responsible for insulin-induced glucose disposal in humans, the rapid loss of the skeletal muscle in males might lead to diminished insulin-induced glucose disposal and exacerbated insulin resistance, resulting in severe glucose abnormalities." (PMID 35909561, 2022). "Insulin resistance exacerbates β-cell dysfunction, reduced glucose uptake further leads to hyperglycemia, and β-cell overburden requires the production of additional insulin as feedback." (PMID 35910625, 2022). "We show that the computational model captures the complex dynamics of glucose-insulin regulation observed in the system, and can provide mechanistic insight into disease progression features, such as insulin resistance and β-cell dynamics." (PMID 36260620, 2022). "L-sulforaphane-rich broccoli sprout powder significantly improved serum insulin concentration, glucose-to-insulin ratio and insulin resistance in type 2 diabetic patients." (PMID 36290791, 2022). "Insulin resistance is often accompanied by hyperinsulinemia, a condition where pancreatic β-cells release excessive amounts of insulin to maintain normal glycaemia." (PMID 35406013, 2022). "As far as DM is considered, SIRT-1 increases insulin signaling and insulin release and prevents insulin resistance through fat mobilization, mTOR signaling, and inflammation control." (PMID 35807828, 2022). "Although insulin resistance and insufficient insulin secretion are essential in T2D development, genetic defects predisposed to both are likely to be important contributors to the disease process." (PMID 35906673, 2022). "In vivo and in vitro animal studies have shown that Alarin reduced insulin resistance and lowered increased insulin and glucose levels." (PMID 35436912, 2022). "The pathogenesis of both conditions are attributed to the continuum dysglycemia with the development of insulin resistance or impaired insulin secretion." (PMID 35578291, 2022). "The mean difference in insulin resistance (-0.32 vs. 0.15), fasting blood sugar (-14.40 vs. 1.68), and fasting insulin (- 2.18 vs. 1.34) were clinically significant in comparison to the control group." (PMID 35999562, 2022). "Impaired pancreatic insulin secretion also leads to insulin resistance and triggers muscle wasting in the Walker 256 cancer cachexia model." (PMID 36105371, 2022). "The outcomes were defined by the studies as being homeostasis model assessment‐insulin resistance (HOMA‐IR), insulin, glucose following glucose tolerance test/oral glucose tolerance test, insulin resistance, insulin sensitivity index, and insulinemia." (PMID 35467075, 2022). "In the present study, we found that exogenous ANP administration significantly ameliorated HFD-induced myocardial insulin resistance, as indicated by the restoration of the insulin-Akt signaling pathway." (PMID 35955507, 2022).
Insulin resistance (continued). "An earlier research study suggested insulin resistance that manifests as impaired insulin-stimulated glucose transport and inhibition of lipolysis in adipose tissue." (PMID 37654824, 2022). "After a 6-week dosage period, various biochemical parameters, as well as HbA1c, antioxidant profile, oral glucose tolerance test (OGTT), insulin sensitivity, histopathology, and insulin resistance, were measured and compared with the untreated diabetic group." (PMID 36304231, 2022). "Body mass index (BMI), serum insulin and insulin resistance, and platelet-to-lymphocyte ratio (PLR), an inflammation prognostic ratio, decreased, whereas TAG/HDL-C and GGT-to-lymphocyte ratio (GLR), an HCC prognostic ratio, increased." (PMID 36293412, 2022). "Insulin resistance is due to a disruption of the intracellular insulin signaling pathway which results in an impaired intracellular glucose uptake." (PMID 36247456, 2022). "Overall, while selenite protects against palmitate-induced insulin resistance in vitro, obesity impedes the effect of selenite on insulin action and adipose tissue metabolism in vivo." (PMID 35624726, 2022). "Skeletal muscle is considered the main site for insulin-stimulated glucose uptake and therefore, a primary target for insulin resistance in the human body." (PMID 35216514, 2022). "Although further studies are needed, dysregulation of phosphate balance potentially impairs insulin signaling to trigger insulin resistance with reduced cellular glucose utilization." (PMID 36364739, 2022). "Concurrently, the Homa index (Homa-IR), which reflects insulin resistance, is increased in both groups, but significantly higher in Black SS than in Whites SS, which confirms that Black SS have lower insulin sensitivity." (PMID 35684085, 2022). "Several studies have shown that reduced insulin clearance is an early adaptation to increased high energy dietary intake, and that it serves to trigger hyperinsulinemia before insulin resistance, obesity, and increased insulin secretion develop." (PMID 36009446, 2022). "Accordingly, a large body of animal studies has confirmed that stress has a role in the insulin secretion from isolated islets of Langerhans and can result in insulin resistance in different tissues." (PMID 36404325, 2022). "Simultaneous measurements of C-peptide and insulin revealed that both insulin resistance and insulin secretion contribute to glucose intolerance in patients with chronic HCV." (PMID 35893594, 2022). "In PWS, we recorded lower levels of fat-free mass (FFM) (p <0.05), fasting (p<0.0001) and 2h post-OGTT insulin (p<0.05) and lower insulin resistance as expressed by homeostatic model of insulin resistance (HOMA-IR) (p<0.0001)." (PMID 35774143, 2022). "Subjects with insulin resistance (n = 101) showed significantly lower nocturnal melatonin levels compared to those with unimpaired insulin secretion (p = 0.006)." (PMID 35140394, 2022). "SSBs also contain rapidly absorbable carbohydrates that affect insulin secretion and blood glucose and possibly later insulin resistance." (PMID 35832052, 2022). "Another study revealed that, dietary intake of sumac powder (6 g/per day) led to significant reduction in fasting serum insulin level as well as insulin resistance condition in type II diabetic patients." (PMID 36014419, 2022). "While women with greater arsenic exposure had greater insulin resistance and lower insulin secretion, effect sizes were small and confidence intervals crossed the null." (PMID 35031057, 2022). "These consequences lead to beta cell dysfunction, decline of insulin secretion and insulin resistance." (PMID 35747779, 2022). "Insulin resistance is characterized by a failure to respond properly to normal levels of circulating insulin in several tissues." (PMID 36555322, 2022).